MIR223 (microRNA 223)
Synonyms: hsa-mir-223; MIRN223; miRNA223; mir-223
Gene: MicroRNA gene on chromosome X (66,018,870 to 66,018,979, forward strand). Ensembl gene ENSG00000284567.
Gene Ontology:
Cellular component: RISC complex
Homologues: Orthologues: chimpanzee ptr-mir-223 (100% identical), macaque mml-mir-223 (97% identical), rat Mir223 (92% identical), dog MIR223 (91% identical), mouse Mir223 (91% identical), guinea pig MIR223 (87% identical), pig ssc-mir-223 (71% identical), tropical clawed frog xtr-mir-223 (66% identical), zebrafish mir223 (62% identical), rabbit MIR223 (58% identical).
Diseases named in the same sentence as MIR223 in open-access papers:
MIR223 is named in the same sentence as 12 diseases in open-access papers, as found by Europe PMC text mining. Sharing a sentence is not in itself a finding about the gene and the disease. The quoted sentences say what the papers report.
Arthritis (1 paper, 2020). Inflammation of a joint. "Mir223 is overexpressed in fibroblast-like synoviocytes, and synovial fluid of the patients with rheumatoid arthritis and lentivirus-mediated silencing of Mir223 can suppress collagen-induced arthritis in mice by decreasing macrophage colony-stimulating factor receptor levels in the synovium." (PMID 33574820, 2020).
autoimmune uveitis (1 paper, 2020). An autoimmune form of uveitis (disease). "In addition to the roles in the granulocytes, Mir223 has been known to be functional particularly in CD4+Th17 cells, which exacerbated the experimental autoimmune uveitis (EAU) by promoting autoreactive Th17 cell responses by inhibiting transcription factor FOXO3 expression." (PMID 33574820, 2020).
Autoimmunity (1 paper, 2025). The occurrence of an immune reaction against the organism's own cells or tissues. "Our study further reveals that transcriptional regulators such as IRF3, IRF7, STAT1, and MYB are critically involved in T cell-mediated autoimmunity, along with ncRNAs LINC00487, LINC01260, and MIR223 with their expression patterns linked to immune dysregulation." (PMID 39844998, 2025).
glomerulonephritis (1 paper, 2020). A renal disorder characterized by damage in the glomeruli. "However, Mir223 deficiency exacerbated glomerulonephritis in B6-Mir223−−-Faslpr/lpr mice by facilitating the infiltration of S1PR1+CD4+ T cells into kidney tissues." (PMID 33574820, 2020).
inflammatory bowel disease (1 paper, 2020). A spectrum of small and large bowel inflammatory diseases of unknown etiology. "Mir223 is essential for innate immune responses and inflammatory diseases such as rheumatoid arthritis and inflammatory bowel disease (IBD)." (PMID 33574820, 2020).
leukemia (1 paper, 2015). A malignant (clonal) hematologic disorder, involving hematopoietic stem cells and characterized by the presence of primitive or atypical myeloid or lymphoid cells in the bone marrow and the blood. "Although these studies collectively show that MIR223 is commonly silenced in leukemia, the contribution of MIR223 loss to disease pathogenesis is unclear." (PMID 25793640, 2015).
lupus (1 paper, 2020). "In conclusion, we presented that the deletion of Mir223 exacerbated the lupus phenotypes associated with increased population of S1PR1+CD4+ T cells and their enhanced infiltration in inflamed kidney tissues." (PMID 33574820, 2020). "Unexpectedly, the deletion of Mir223 exacerbated the lupus phenotypes associated with increased population of S1PR1+CD4+ T in spleen and the enhanced infiltration of S1PR1+CD4+ T cells in inflamed kidney tissues, suggesting compensatory role of Mir223 in the pathogenesis of lupus nephritis." (PMID 33574820, 2020). "Overlapping abnormality in neutrophils by Mir223 deficiency and SLE was thought to be one of the causes of exacerbation of lupus nephritis in our B6-Mir223−/−Faslpr/lpr mice." (PMID 33574820, 2020).
lupus nephritis (1 paper, 2020). Glomerulonephritis in the context of systemic lupus erythematosus. "We initially hypothesized that Mir223 deficiency may ameliorate lupus nephritis since MIR223 is overexpressed in CD4+ T cells in the patients with relapsing multiple sclerosis and rheumatoid arthritis." (PMID 33574820, 2020).
metastatic melanoma (1 paper, 2024). A melanoma that has spread from its primary site to another anatomic site. "By evaluating 74 PRGs (except for MIR223), we found that these genes showed distinct expression patterns in primary and metastatic melanoma from the TCGA-SKCM cohort." (PMID 38229080, 2024).
myeloproliferative disorder (1 paper, 2015). A clonal hematopoietic stem cell disorder, characterized by proliferation in the bone marrow of one or more of the myeloid (i.e., granulocytic, erythroid, megakaryocytic, and mast cell) lineages. "We show that Mir223 loss results in a modest expansion of myeloid progenitors, but is not sufficient to induce a myeloproliferative disorder." (PMID 25793640, 2015).
MIR223 also shares sentences with these, for which no sentence is quoted: infection (1 paper); rheumatoid arthritis (1).